RETN (resistin)
Diseases named in the same sentence as RETN in open-access papers (continued):
Sharing a sentence is not in itself a finding about the gene and the disease.
tumor (continued). "Previously, we found that resistin was a functional downstream target of TAZ (a transcription cofactor) that facilitated tumorigenesis of BC by increasing tumor stemness." (PMID 36765683, 2023). "Abundant studies have found that adipocytokines play important roles in tumor invasion and metastasis, among which resistin and leptin have been shown to promote metastasis in a variety of tumor models." (PMID 36361525, 2022). "In a study by Li Pang and Xiaohan Chang on 50 EOC specimens, it was shown that higher resistin expression is positively correlated with the histological differentiation of the tumor and the occurrence of lymph node metastases." (PMID 35453670, 2022). "It is worth mentioning that the level of resistin in the tumor microenvironment of neoplastic tissues was higher than in the serum and was correlated with tumor progression." (PMID 35453670, 2022). "RETN is also involved in tumor progression through the activation of inflammation and the expression of adhesion molecules, promoting the proliferation, metabolism and invasion of tumor cells." (PMID 33859244, 2021). "Cytokines released from adipose tissue such as adipokines, leptin, and resistin, among others, are also believed to facilitate tumor progression." (PMID 34212054, 2021). "In domestic animals, the origin of resistin has not yet been documented and little is known about the pathophysiological mechanisms that involve resistin in neoplasms." (PMID 32903534, 2020). "Coincidently, adipocytic TAZ/Resistin is strongly correlated with advanced clinical stage, especially T stage, demonstrating the critical tumor-supporting role of adipocytes on TNBC." (PMID 33318171, 2020). "We observed a significantly increased tumor volume (p < 0.05) in the mice that were administered resistin." (PMID 30131543, 2018). "We further validated our results in vivo where resistin administration significantly enhanced tumor growth in mice." (PMID 30131543, 2018). "High level of resistin expression correlated with increased tumor stage, size, and lymph node metastasis." (PMID 27314854, 2016). "Association of ERM with enhanced tumor cell invasion raises several questions regarding the mechanism by which resistin can promote tumor cell invasion." (PMID 26729407, 2016). "To examine if resistin correlated with aggressive tumor subtypes, we divided the entire population sample set by receptor status." (PMID 27314854, 2016). "Combined with the observation that vimentin is critical for tumor metastasis, the findings of our current study indicated that resistin induces tumor invasion via ERM-mediated vimentin induction." (PMID 26729407, 2016). "There was a weak positive correlation between serum resistin concentrations and its levels in tumor tissue (r = 0.31, P = 0.024)." (PMID 25049439, 2014). "Several colorectal cancer studies have shown a positive correlation between resistin and tumor size based on T-staging and tumor grading." (PMID 24829560, 2014). "A weak positive correlation between serum resistin concentration and its level in tumor tissue was observed." (PMID 25049439, 2014). "Both SE and EE tumor-bearing mice presented a significant increase in systemic inflammatory markers, including, IL-6, TNF-α, MCP-1, PAI-1 and resistin very likely due to the presence of the tumor." (PMID 23272114, 2012). "If focused solely on males, this trend was even stronger (correlation of resistin with T-staging in males: r=0.70; p<0.01; correlation of resistin with tumor grading in males: r=0.56; p<0.01)." (PMID 23173608, 2012). "Further, we found a positive correlation of resistin and tumor size based on T-staging in CRC males." (PMID 23173608, 2012). "Adipokines such as chemerin, resistin, leptin, and apelin contribute to tumour progression." (PMID 42135288, 2026).
tumor (continued). "This review discusses the aberrant expression of resistin and its receptors, its diverse downstream signaling, and its impact on tumor growth, metastasis, angiogenesis, and therapy resistance to support its clinical exploitation in biomarker and therapeutic development." (PMID 39184804, 2024). "Resistin is an inflammo-regulatory protein that is involved in tumor progression." (PMID 38730433, 2024). "RETN has a significant impact on tumor growth, metastasis, angiogenesis, and therapy resistance." (PMID 38600248, 2024). "Inhibition of resistin could potentially reduce tumor growth, attenuate inflammation, and improve insulin sensitivity in CRC." (PMID 39184804, 2024). "In neoplastic diseases, resistin may enhance neoangiogenesis and metastasis by modulating vascular endothelial growth factor (VEGF) secretion." (PMID 36834693, 2023). "In addition, different studies have reported a correlation between high serum resistin levels, tumor grade and CRC prognosis." (PMID 37760840, 2023). "Furthermore, CSRNP1 and RETN were down-regulated in tumor tissues, but the down-regulation of both predicted a better prognosis." (PMID 36401283, 2022). "Moreover, a positive correlation between the expression of resistin in neoplastic tissue and the histological differentiation (grade) of a tumor, the tumor size, and the condition of the lymph nodes has been demonstrated." (PMID 35453670, 2022). "Moreover, LEP and RETN affect tumor progression by promoting anti-apoptotic and angiogenic factors as well as production of pro-inflammatory cytokines." (PMID 36362348, 2022). "Evidence from previous studies also suggest that resistin could be an essential modulator in tumor growth and chemoresistance." (PMID 33651847, 2021). "Accumulating evidence indicates that resistin regulates tumor progression and metastasis." (PMID 30631040, 2019). "The objective of our study was to determine whether resistin directly regulates invasion of tumor cells, and if so, what are the molecular signaling pathways are involved in the process." (PMID 26729407, 2016). "In addition, intra-tumor heterogeneity would have to be considered to determine if resistin has potential as a tissue biomarker." (PMID 27314854, 2016). "However, resistin level in tumor tissue was marginally higher than in the matched macroscopically normal mucosa." (PMID 25049439, 2014). "Although resistin promotes in vitro angiogenesis of human endothelial cells directly, however, the role of resistin in tumor angiogenesis still remains unclear." (PMID 23652833, 2013). "However, SE and EE tumor-bearing mice showed significant increases in resistin compared to those in SE and EE non-tumor-bearing mice." (PMID 23272114, 2012). "Thus, to the best of our knowledge, in this study, we report for the first time the predictive value of the immunohistochemical (IHC) status of leptin, leptin-R, adiponectin, and resistin together on tumor characteristics and outcomes in a cohort of 81 RCC patients who were treated with nephrectomy." (PMID 41010935, 2025). "However, there is less research on resistin expression in tumor tissues." (PMID 40002704, 2025). "For example, increased levels of the adipocyte‐related hormone, resistin, the pro‐inflammatory cytokine, IL‐6, and the CC chemokine, CCL2, within the TME of AA women gives rise to an increased density of M2 macrophages, also known as tumor‐associated macrophages." (PMID 36632988, 2023). "Given that the lymph node status existed at presentation and all patients received chemotherapy, we considered whether the overexpression of resistin per se may have influenced the tumour micro-environment to exert a suppressive effect on tumour cell motility or extravasation." (PMID 29566726, 2018).
tumor (continued). "The association of anti-inflammatory ‘M2-like’ monocytes and macrophages with metastases in preclinical models provides a possible mechanism whereby increased resistin levels could lead to a lower potential for metastatic spread by promoting a pre-existing pro-inflammatory tumour microenvironment." (PMID 29566726, 2018). "These potent adipokines such as resistin, leptin, and adiponectin are involved in cell growth, proliferation, cell cycle control, and angiogenesis and could play a significant role in facilitating tumor growth and metastasis." (PMID 28168205, 2017). "Moreover, different cells in the tumor microenvironment can produce resistin, therefore varying numbers of adipocytes and immune cells present in the tumor microenvironment could account for the changes in resistin gene expression levels." (PMID 27314854, 2016). "Several studies indicated that adipose tissue itself is an endocrine organ that could influence tumour growth or differentiation via adipose tissue-derived hormones called adipocytokines, e.g., leptin, resistin, or adiponectin (ApN), most of which showed strong correlations with BMI." (PMID 26959740, 2016). "Markers such as chemerin, TSP-1, PON-1, resistin, and MPO correlate with tumour burden and disease activity, while adiponectin and TSP-1 are linked to treatment response." (PMID 41303900, 2025). "In this research, the ERGS was composed of 8 ERGs (CXCL9, CYP17A1, DRGX, ENTHD1, HAS1, LAIR2, RETN, and SPHKAP), some of which were pivotal to the tumor progression." (PMID 38600248, 2024). "This article reviews the potential role of resistin in the pathogenesis of CRC and its impact on tumor progression." (PMID 39184804, 2024). "Conversely, levels of apelin, CCL2, progranulin, interleukin-6, chemerin, retinol binding protein 4 (RBP4), resistin, and plasminogen activator inhibitor-1 (PAI-1) expression were lower in tumor tissue than in adjacent normal tissue." (PMID 36917086, 2023). "Our current study provides a novel link between resistin and CXCL5 under the consideration of cell–cell interaction in the tumor microenvironment." (PMID 36104403, 2022). "Strongly positive resistin expression is related to multiple poor prognostic factors in CRC, including depth of tumor invasion, lymph node metastasis, and tumor stage." (PMID 32420377, 2020). "For example, positive resistin expression was correlated with larger tumor size, higher tumor grade, higher clinical stage, and HER2-positive expression; strongly positive resistin expression was correlated with higher tumor grade and HER2-positive expression." (PMID 33313320, 2020). "Our previous investigations echo other reports describing how resistin and EGFR promote tumor progression through downstream p44/p42 MAPK (ERK1/2) signaling." (PMID 33313320, 2020). "qPCR analysis indicated higher levels of resistin and VEGF-A expression in tumor specimens compared with normal cartilage and lower levels of miR-16-5p expression in tumor specimens compared with normal tissue." (PMID 30631040, 2019). "Previous studies have reported that resistin stimulates the growth of many tumors by promoting the secretion of VEGF-A, which promotes tumor invasion." (PMID 31719210, 2019). "However, the role of resistin in tumor angiogenesis is largely unknown." (PMID 30631040, 2019). "We show that resistin supports tumor growth in an in vivo mouse model with data suggesting induction of EMT and stemness markers in tumor remnants." (PMID 30131543, 2018). "In the present study, only a modest positive correlation between RETN and CAP1 tumor expression was found." (PMID 30524378, 2018). "Therefore, even in patients with the same tumor type, resistin expression levels might vary." (PMID 27314854, 2016). "Combined with a recent report showing that ERM is critical for tumor cell invasion, these findings implicate a role for ERM in resistin-mediated tumor cell invasion." (PMID 26729407, 2016).
tumor (continued). "Serum resistin levels also were positively correlated with TNM, tumor size, LN metastasis, and histological grading (r = 0.395, P = 0.014; r = 0.429, P = 0.007; r = 0.575, P = 0.000; and r = 0.509, P = 0.000)." (PMID 25838618, 2015). "Our results indicated that resistin induced up-regulation of MMP-2 expression and tumor metastasis by down-regulation of miR-519d through the AMPK/p38 pathway." (PMID 25404641, 2015). "Only in postmenopausal subgroups, leptin, resistin, and visfatin levels were positively correlated with TNM staging, tumor size, lymph node (LN) metastasis, and histological grading." (PMID 25838618, 2015). "As shown, pathways of PD‐L1, GP1BA, RESISTIN and SPP1 are exclusively activated in tumour." (PMID 39934971, 2025). "Conversely, leptin and resistin, which are pro-inflammatory adipokines, contribute to tumour-promoting processes by activating the PI3K/Akt/mTOR signalling pathway, thereby sustaining tumour cell survival, growth, and invasion." (PMID 41002741, 2025). "The RESISTIN and MIF pathways in MDSCs and epithelial cells were also enhanced; they may contribute to the chemotaxis of tumor-infiltrating immune cells." (PMID 39722065, 2025). "A previous study showed that the resistin levels in CRC patients were significantly higher than a matched control group, and the concentration of resistin gradually increased as the tumor stage progressed, which indicated that resistin is a convincing biomarker for the progression of CRC malignancy." (PMID 35890097, 2022). "However, PNETs are known to be a particularly metabolically active tumor type, and our analysis indicated that MK2 affects macrophage-dependent production of metabolic factors such as insulin, leptin and resistin in PNETs." (PMID 36362348, 2022). "In addition, the serum resistin levels of patients with breast cancer, CRC, and lung adenocarcinoma gradually increase in the process of tumor progression." (PMID 35890097, 2022). "We found that resistin expression was positively correlated with pathological grade and LN metastasis, regardless of age, histological type, residual tumor size, and clinical stage." (PMID 34659568, 2021). "In addition, this paper also briefly describes the mechanism of action of the other three adipokines, resistin, MIF and MCP-1 in tumor and their therapeutic strategies." (PMID 34485124, 2021). "Although the mechanism of action of resistin is still unclear, it does not prevent us from using it as a target for tumor therapy." (PMID 34485124, 2021). "Although this correlation is not well-understood, it is known that resistin promotes epithelial and mesenchymal multiplication in the breast parenchyma, which are critical mechanisms for tumor development and metastasis." (PMID 32903534, 2020). "In this study, we examined how resistin affects VEGF-A expression and tumor angiogenesis." (PMID 31719210, 2019). "Also, since our in vitro results suggested an effect of resistin on EMT and stemness markers, we evaluated the levels of molecular markers of EMT and stemness in tumor remnants as well." (PMID 30131543, 2018). "Other studies show that resistin regulates production of the matrix metalloproteinases (MMPs) and modulates the secretion of vascular endothelial growth factor (VEGF), which is considered of importance for promoting tumor invasion." (PMID 27642602, 2016). "Both tumor-bearing groups (SE and EE housing) had increased resistin, IL-6, TNF-α, PAI-1 and MCP-1 levels irrespective of the different housing environment demonstrating higher inflammatory response due to the presence of the tumor." (PMID 23272114, 2012). "Concurrently, both in vitro and in vivo studies have demonstrated that resistin promotes the expression of VEGF-A and angiogenesis within the tumor microenvironment by inhibiting the expression of miR-5-3p through the PI3K/Akt signaling cascade, thus affecting tumor bone metastasis." (PMID 38571500, 2024).
tumor (continued). "Serum resistin concentrations have not been shown to be related to the degree of dysplasia, histologic differentiation, or tumor location, but have been shown to increase gradually with tumor stage progression." (PMID 39184804, 2024). "Increasing research indicates that adipokines (such as leptin, resistin, visfatin, etc.)and inflammatory factors (such as IL-1β, IL-6, chemokines, FABP4, etc.)secreted by BMA can also regulate angiogenesis, indirectly facilitating the progression of tumor bone metastasis." (PMID 38571500, 2024). "In addition, resistin can promote angiogenesis by inducing the expression of vascular endothelial growth factor (VEGF) and increasing the expression of matrix metalloproteases, which contribute to tumor vascularization and promote cell invasion and metastasis." (PMID 39184804, 2024). "However, despite the high frequency of CBMT in the oncology routine, according to our knowledge, there are no studies on the possible participation of resistin in this tumor progression." (PMID 32903534, 2020). "However, the tumor resistin expression will not reflect the accumulated exposure to circulating resistin levels over time, for which additional analyses in serum samples would be required." (PMID 30524378, 2018). "At last, we did not rule out residual confounders that may alter resistin levels, including lifestyle parameters such as smoking, alcohol, exercise, nutritional habits, and clinicopathological features such as tumor stage, localization, and type." (PMID 27642602, 2016). "There was no relation between tumor resistin and clinic-pathological parameters." (PMID 25049439, 2014). "In addition, resistin promotes tumor angiogenesis and progression by inducing vascular endothelial growth factor (VEGF) expression and increasing the expression of matrix metalloproteases, which contribute to tumor vascularization, cell invasion, and metastasis." (PMID 39184804, 2024). "Hence, we pose the question of whether classical adipokines including resistin and adiponectin interfere equally profoundly with the course of PC by regulating TME, tumor metabolic reprogramming, and other pathways, which needs to be further determined by future studies." (PMID 35875143, 2022). "No similar relationship was found between the level of resistin and the histological type of the tumor, the FIGO stage, age, the residual tumor after initial laparotomy, and the level of the antigen Ca125 in the serum." (PMID 35453670, 2022). "MSGN1, ISM2, HAS1, RETN, MMP19, C1QTNF1, and F13A1 were all involved in the regulation of tumors, but their involvement in the regulation of tumor immunity is not clear." (PMID 34177903, 2021). "However, resistin expression was not correlated with age, FIGO stage, or residual tumor after initial laparotomy (P > 0.05)." (PMID 34659568, 2021). "Also, in postmenopausal controls and cases there were positive correlation of leptin, resistin, and visfatin and negative correlations of adiponectin with TNM, tumor size, LN metastasis, and histological grade." (PMID 25838618, 2015).